EWSR1 (EWS RNA binding protein 1)
Diseases named in the same sentence as EWSR1 in open-access papers (continued):
Sharing a sentence is not in itself a finding about the gene and the disease.
Ewing sarcoma (continued). "In this study, the largest multi-omic assessment of EWSR1-NFATc2 fusion positive sarcomas to date, our data reinforces previous findings that EWSR1-NFATc2 fusion positive sarcomas are molecularly distinct from standard Ewing sarcomas." (PMID 34021224, 2021). "Ewing sarcoma is a pediatric bone cancer that expresses the chimeric protein EWSR1/FLI1." (PMID 33293370, 2021). "The EWSR1-FLI-1 fusion is observed in 85% of Ewing’s sarcoma cases." (PMID 32899796, 2020). "Indeed, in many ways, this survey supports this idea as the majority of respondents felt that patients with the various EWSR1-ETS fusions should accrue on Ewing sarcoma clinical studies." (PMID 33488267, 2020). "Ewing sarcoma is an aggressive cancer of the bone and soft tissues resulting from the fusion of Ewing sarcoma RNA Binding Protein 1 (EWSR1) to Friend leukemia integration 1 transcription factor (FLI1) (85%) or E-twenty-six-related (ETS-related) gene (ERG) (15%)." (PMID 32290418, 2020). "Molecularly, it is characterized by a chromosomal translocation generating a driver fusion gene between the gene EWSR1 (Ewing Sarcoma Breakpoint Region 1) and one gene from the E26 transformation-specific or E-twenty-six (ETS) family (FLI1 in most of the cases), with few other genomic alterations." (PMID 32225029, 2020). "Despite Ewing sarcoma being characterized by specific EWSR1-ETS gene fusions resulting in oncogenic transcription factors, currently, no targeted therapy could be implemented." (PMID 31370265, 2019). "In contrast to osteosarcoma, Ewing sarcoma is characterized by a chromosomal translocation between the EWSR1 and FLI1 genes in 90% of cases, or by the fusion of EWSR1 with other transcription factors of the E26 Transformation-Specific (ETS) gene family in 10% of cases." (PMID 31370265, 2019). "Like other proteins of the FET family (FUS, EWSR1 and TAF15; Ewing’s sarcoma (EWS) and TAF15 (TATA-binding protein-associated factor), mutations in fused in sarcoma (FUS) are directly linked with protein aggregation in amyotrophic lateral sclerosis (ALS) and frontotemporal dementia patients." (PMID 31238957, 2019). "Ewing sarcoma is characterized by the presence of chimeric EWSR1-ETS fusion oncogenes." (PMID 29416716, 2018). "Testing for the EWSR1 mutation confirms the diagnosis of Ewing sarcoma and excludes other types of embryonal CNS tumors." (PMID 29285586, 2018). "The fusion gene includes EWSR1 in chromosome 22 (as noted in the earlier section about Ewing sarcomas), and thus IGF1R expression might be a clue for distinguishing CCS from melanoma." (PMID 30487384, 2018). "Ewing sarcoma is genetically defined by pathognomonic EWSR1-ETS fusion transcripts." (PMID 29416716, 2018). "The EWSR1/FLI1 and EML4/ALK1 translocation common in solid tumors such as Ewing Sarcoma and lung cancer, could also generate associated f-circRNAs." (PMID 28279183, 2017). "Ewing sarcoma is most commonly characterized by the EWSR1-FLI1 or EWSR1-ERG translocation." (PMID 29050367, 2017). "These types of variants are not generally detected with commercial amplicon-based NGS panels, despite being of critical importance for the clinical management and diagnosis of paediatric patients (e.g. MYCN amplification in neuroblastoma, EWSR1 in Ewing’s sarcoma)." (PMID 29340109, 2017). "Ewing sarcoma remains such a monster, a “genetically engineered monster” with the EWSR1-ETS gene fusion as the major driver of its nefarious activities, as Paul Meltzer pointed out while introducing the topic of “Spatial and temporal genetic and non-genetic diversity of Ewing sarcoma”." (PMID 26802024, 2016). "Ewing sarcoma (ES) is an aggressive tumor defined by EWSR1 gene fusions that behave as an oncogene." (PMID 27317769, 2016). "Ewing sarcoma is characterized by IGF pathway activating translocations of the EWSR1 gene." (PMID 23383402, 2013).
Ewing sarcoma (continued). "Adamantinoma-like Ewing sarcoma (ALES) is a rare malignant neoplasm, identified as a type of Ewing sarcoma (ES), characterized by the EWSR1::FLI1 translocation and a complex immunoprofile." (PMID 40225424, 2025). "Mimicking Ewing sarcoma in mice has been challenging, however, a recent mouse model showed that while EWSR1::FLI1 may be sufficient for tumorigenesis, subsequent YAP1 activation induced by IGF1 signalling may be required for the activation of TEAD driven transcription and metastatic progression." (PMID 40442778, 2025). "Ewing sarcoma family of tumors (ESFTs), which includes Ewing sarcoma and primitive neuroectodermal tumors (PNETs), is a group of aggressive malignant neoplasms characterized by small round blue cells and fusion of the ​​​​​​EWSR1 gene with other genes such as FLI1 and ERG." (PMID 40416106, 2025). "Similarly, lurbinectedin has shown preclinical effects on EWSR1::FLI1 in Ewing sarcoma." (PMID 39139449, 2024). "Interestingly, EWSR1-ETS fusions are quite common in Ewing sarcomas." (PMID 38716144, 2024). "This smaller allele is more frequent in populations with African origin where Ewing sarcoma incidence is tenfold lower than in Caucasian populations where the small EWSR1 allele is not present, suggesting the critical role of intronic Alu elements in EWSR1-related chromosome rearrangements." (PMID 39769457, 2024). "Genetically, Ewing sarcoma is driven by a fusion oncoprotein that results from one of a small number of chromosomal translocations composed of a FET gene and a gene encoding an ETS family transcription factor, with ~85% of tumors expressing the EWSR1::FLI1 fusion." (PMID 36672331, 2023). "Ewing Sarcoma (ES) is a primitive small round cell sarcoma defined by fusions involving members of the FET (predominantly EWSR1 or FUS) and ETS (most commonly including FLI1, ERG, ETV1, ETV4, or FEV) gene families." (PMID 35059992, 2022). "Similarly, complex gene fusion generating rearrangements have been reported in solid tumors, such as EWSR1::ERG and some EWSR1::FL11 fusions in Ewing sarcoma, wherein the rearrangements involve inversions and other complex rearrangements rather than simple reciprocal translocations." (PMID 35158889, 2022). "Ewing sarcoma (ES) is the prototypical SBRCT characterized by the fusion of EWSR1 and a member of the ETS family of transcription factors." (PMID 35568949, 2022). "Ewing sarcoma family tumors are characterized by the presence of reciprocal chromosomal translocations that fuse a member of the FET family of RNA-binding proteins (encoded by FUS, EWSR1, and TAF15), with different members of the ETS (E26-specific) family of transcription factors." (PMID 35285802, 2022). "However, the diminished effects of a loss of EWSR1 found by the lengthier shRNA knockdown protocol motivated us to pursue additional approaches to test potential functions shared by EWSR1 and EWS-FLI1 in Ewing sarcoma." (PMID 34035145, 2021). "Therefore, mitotic dysfunction induced by EWSR1/FLI1 may play a critical role in the induction of Ewing sarcoma." (PMID 33293370, 2021). "Ewing Sarcoma (ES) is characterized by recurrent translocations between EWSR1 and members of the ETS family of transcription factors." (PMID 31550266, 2019). "The EWSR1-FLI-1 fusion protein pathognomonic for Ewing sarcoma (ES) binds the promoter of histone methyltransferase (HMT) enhancer of Zeste, Drosophila, Homolog 2 (EZH2) to promote expression in ES." (PMID 28654693, 2017). "In addition, haploinsufficiency of the EWSR1 gene in Ewing sarcoma tumors may also contribute to an impaired response to DNA damage." (PMID 27557498, 2016). "Hence, it is possible that EWSR1 translocations could exert a dominant negative function over endogenous EWSR1, leading to RS and genomic instability in Ewing sarcomas." (PMID 27577084, 2016).
Ewing sarcoma (continued). "Ewing Sarcoma (ES) is a mesenchymal malignancy of unclear histogenetic derivation characterized by distinct chromosomal translocations at the EWSR1 gene; this disease occurs primarily in children and young adults and less commonly in older adults." (PMID 26199562, 2015). "Finding EWSR1 translocation can be very useful for deciding upon therapeutic management but an expansion in molecular disease identifiers is required particularly when one considers the combinatorial diversity among chromosomal breakpoints in Ewing sarcoma/PNET tumours." (PMID 22587874, 2012). "LSD1 and the pathognomonic fusion oncoprotein, EWSR1::FLI1, colocalize throughout the genome, suggesting that LSD1 is a critical co-regulator driving the progression of Ewing sarcoma." (PMID 41732136, 2026). "A chromosomal translocation between the EWSR1 and ETS genes is the key oncogenic driver in Ewing sarcoma." (PMID 41002248, 2026). "We have recently demonstrated that genetic inactivation of EWSR1 : : FLI1 by CRISPR/Cas9, successfully blocks cell proliferation in a cell model of Ewing sarcoma." (PMID 40089636, 2025). "Here, we use the term hegemonic (from the Greek hēgemonikos, meaning ruling, dominant, or supreme) to describe the overarching influence of the EWSR1::ETS oncoprotein, which overrules the CRC principles in Ewing sarcoma." (PMID 41444391, 2025). "Our findings indicate a genome-wide gain of H3K27me3 in relevant genes from EWSR1::FLI1 pathways, supporting the important role of EZH2 in Ewing sarcoma tumorigenesis." (PMID 41085408, 2025). "In line with previous transcriptomic studies, EWSR1::FLI1-KD cells formed an intermediate population, bridging Ewing sarcoma cell lines and MSCs." (PMID 41444391, 2025). "Altogether, the hegemonic EWSR1::ETS fusion oncoprotein operates upstream of the predicted CRC, represents a key vulnerability, and drives Ewing sarcoma identity." (PMID 41444391, 2025). "FET (FUS, EWSR1, and TAF15) fusion oncoproteins are characteristic for several sarcomas and leukemias, including myxoid liposarcoma and Ewing sarcoma." (PMID 40988026, 2025). "The prototype of the characteristic histomorphology of small round cell sarcomas is the Ewing Sarcoma, which is exemplary defined by the chromosomal translocation of an FET gene family member with an ETS transcription factor, mostly EWSR1::FLI1." (PMID 40134582, 2025). "PC1 primarily separated MSC and EWSR1::FLI1-KD samples from the other entities, while PC2 segregated Ewing sarcoma samples." (PMID 41444391, 2025). "Other non-osteosarcomatous malignancies occurring in the jawbones primarily included conventional and mesenchymal chondrosarcoma, Ewing sarcoma, TFCP2::EWSR1-rearranged rhabdomyosarcoma, and odontogenic neoplasms such as ameloblastic fibrosarcoma." (PMID 40526340, 2025). "In this study, upon expression of EWSR1::FLI1 in human pediatric mesenchymal stem cells, considered the putative cell of origin of Ewing sarcoma, we unraveled the genome-wide redistribution of H3K27me3." (PMID 41085408, 2025). "Further, in vivo delivery of an EWSR1::FLI1 disrupting dual intron targeting system led to lower Ki67 proliferative index, higher levels of cleaved caspase-3 and prolonged survival in an Ewing sarcoma mouse model." (PMID 41190236, 2025). "Ewing sarcoma (ES) is driven by the oncogenic fusion-protein EWSR1::FLI1." (PMID 39894896, 2025). "The most frequent gene fusion identified in Ewing sarcoma is EWSR1::FLI1 fusion, and the second most common fusion is EWSR1::ERG." (PMID 40861426, 2025). "For example Ewing sarcoma, involving FET::ETS fusions (primarily EWSR1::FLI1), is predominantly a tumor of adolescents and young adults." (PMID 40852926, 2025). "KDM6A had a demethylase-independent role in recruiting BRG1 at EWSR1::FLI1-primed enhancers containing single GGAA motifs, which was critical for Ewing sarcoma tumor growth." (PMID 41085408, 2025).
Ewing sarcoma (continued). "Having shown that seclidemstat largely recapitulates the transcriptional effects of SP-2509, we also wanted to determine the degree to which seclidemstat disrupts EWSR1::FLI1 transcriptional activity and LSD1 function in Ewing sarcoma cells." (PMID 40852926, 2025). "A study in Zebrafish reported that conditional expression of the EWSR1::FLI1 transgene in a trunk neural crest cell may cause transcriptional hijacking and mesoderm lineage reprogramming, which might underlie the formation of neoplasms reminiscent of human Ewing sarcoma." (PMID 40442778, 2025). "In Ewing sarcoma, a CRC including KLF15, TCF4, and NKX2-2 MTFs that cooperate with EWSR1::FLI1 was reported in A-673 and EW-8 cells." (PMID 41444391, 2025). "To gain insight into the role of both demethylases on the EWSR1::FLI1 transactivation activity, we knocked down KDM6A and KDM6B in two Ewing sarcoma cell lines, A-673 and TC-71, using a doxycycline-inducible system." (PMID 41085408, 2025). "In Ewing sarcoma, FET::ETS gene fusions, most commonly EWSR1::FLI1, are generated either by balanced chromosomal translocations or loop like rearrangements termed chromoplexy." (PMID 40442778, 2025). "In Ewing sarcoma, the LCD of the EWSR1 protein fuses to the DNA-binding domain of an ETS transcription factor (e.g., FLI1), forming the EWSR1::FLI1 fusion oncoprotein." (PMID 41294805, 2025). "The results clearly demonstrated a EWSR1::FLI1 (E7F5) fusion with breaking points at an RNA level after ESWR1 exon 7 and before FLI1 exon 5, thereby resulting in a diagnosis of a Ewing sarcoma." (PMID 39575427, 2024). "The Ewing sarcoma family of tumors comprises Ewing sarcoma (EWS) and primitive neuroectodermal tumors (PNETs), and is characterized by chimeric proteins derived from the EWSR1 gene." (PMID 39199601, 2024). "In diverse tumor types including Ewing sarcoma (ES), Desmoplastic Small Round Cell tumor (DSRCT), and Clear cell sarcoma (CCS), EWSR1 is expressed as a fusion transcription factor resulting in distinct morphologies and tissue lineages." (PMID 38946804, 2024). "For example, EWSR1/FUS::NFATC2 sarcomas feature a marked male predilection, and EWSR1::PATZ1 sarcomas can arise in a broad age range, in contrast to Ewing sarcoma." (PMID 38339014, 2024). "NGS of the DNA from the biopsy tissue detected a EWSR1::FL1 fusion gene, which confirmed the initial diagnosis of Ewing sarcoma." (PMID 39575427, 2024). "Ewing sarcoma is defined by a pathognomonic translocation of the EWSR1 gene with one of the ETS family of genes, most commonly EWSR1::FLI1." (PMID 38775200, 2024). "The FET-family proteins (including FUS, EWSR1, and TAF15) contain a PrLD that is conserved in the FET-translocated sarcomas, including in Ewing sarcoma." (PMID 38611033, 2024). "EWSR1::FLI1 can exert both activating and repressing functions, and both of these functions are of importance in Ewing sarcoma." (PMID 38611033, 2024). "Although the effect of the hnRNPH1 silencing seemed modest, EWSR1::FLI1 levels increased and Ewing sarcoma cell line proliferation was dramatically reduced." (PMID 36793594, 2023). "CD44s, upregulated upon EWSR1::FLI1 knockdown, regulates cell migration and invasion in Ewing sarcoma cells." (PMID 37511533, 2023). "Multiple E3 ubiquitin ligases have been observed to mediate EWSR1::FLI1 ubiquitination and degradation in Ewing sarcoma, including TRIM8 and SPOP." (PMID 36672331, 2023). "Together, currently a commonly accepted standard for the diagnosis of Ewing sarcoma includes a consistent histological morphology, staining for CD99, and evidence of EWSR1 rearrangement by fluorescence in situ hybridization, PCR or sequencing." (PMID 36672331, 2023). "UNC4151 decreased FAIRE signal at EWSR1::FLI1-bound loci and both MS2616 and UNC4151 decreased cell viability in Ewing sarcoma cells in a concentration-dependent manner similar to MS0621." (PMID 36793594, 2023).
Ewing sarcoma (continued). "Deletion of LIN28B led to decreased EWSR1::FLI1 expression, which affects the self-renewal and tumorigenicity of Ewing sarcoma cells." (PMID 36672331, 2023). "HNRNPH1 binds to the G-rich sequences and destabilizes the G4-RNA structures formed by EWSR1-exon 8 and mediates its exclusion from the oncogenic EWS-FL1 transcripts in Ewing sarcomas." (PMID 37323535, 2023). "Fifteen Ewing sarcoma PDX were established, 13 displayed the EWSR1::FLI1 translocation, one each FUS::ERG and EWSR1::FEV." (PMID 37723198, 2023). "Recently, we identified 7Ai, a putative small-molecule OTUD7A inhibitor that suppresses EWSR1::FLI1 protein expression and subsequent Ewing sarcoma cell and tumor growth." (PMID 36672331, 2023). "A classic example of transcription factor fusion is the EWSR1::FLI1 fusion, which is a common driver in Ewing sarcoma." (PMID 37509339, 2023). "The EWSR1/FLI1 fusion protein, which is identified in 85–90% of Ewing sarcoma tumors, and its direct targets are given special focus in this study." (PMID 35454895, 2022). "The rearrangement of the RNA-binding protein EWSR1 characterizes a variety of malignant tumors, including Ewing’s sarcoma (EWSR1/ETS), depilated small round cell tumor (EWSR1/WT1), and some acute lymphoblastic leukemia (EWSR1/ZNF384)." (PMID 35686089, 2022). "Recently, CSCs were identified in the closely related Ewing sarcoma, which like DSRCT is characterized by chromosomal translocations involving EWSR1 (most commonly the EWSR1-FLI1 translocation)." (PMID 36506091, 2022). "For instance, fusions involving EWSR1 and FLI1 drive Ewing sarcoma, which makes up 36.9% of bone cancers in AYAs compared to 12.3% in OAs." (PMID 36433963, 2022). "Illustrative examples include Ewing sarcoma (EWS), defined by fusions of the EWSR1 gene with one of the ETS transcription factor genes and fusion-positive rhabdomyosarcoma (RMS), expressing PAX3- or PAX7-FOXO1 (PAX3/7-FOXO1) fusion transcripts." (PMID 35347250, 2022). "The present study therefore constitutes a biologically driven indication that the EWSR1–ETS fusion, which is pathognomonic of Ewing sarcoma, constitutes a strong predictive biomarker of statin sensitivity." (PMID 35565457, 2022). "Most ES cases carry the fusion of the Ewing Sarcoma Breakpoint Region 1 (EWSR1) and FLI1 (Friend leukemia virus integration site 1) genes, leading to an EWS–FLI1 fused protein, which is associated with autophagy, a homeostatic and catabolic mechanism under normal and pathological conditions." (PMID 33652741, 2021). "EWS RNA binding protein 1/Fli-1 proto-oncogene, ETS transcription factor regulates EYA3 in Ewing sarcoma via modulation of miR-708, resulting in increased cell survival and chemoresistance." (PMID 34395419, 2021). "We developed a novel RT–PCR assay that can efficiently detect both EWSR1-ETS and FUS-ETS observed in Ewing sarcoma." (PMID 34749732, 2021). "The fact that FEZF1 was expressed at high levels in all Ewing sarcoma cells tested, excepting the Ewing sarcoma cell line CADO-ES1 harboring an EWSR1-ERG fusion, suggest that FEZF1 can play a relevant role in Ewing sarcoma pathogenesis." (PMID 34830820, 2021). "Consistent with our previous report using Ewing sarcoma A673 cells and HeLa cells, the DLD-1 cells that were induced to express EWSR1/FLI1 (Dox+) displayed a greater incidence of aberrant Aurora B localization than uninduced (Dox-) cells." (PMID 33293370, 2021). "Investigation of the upstream regulatory mechanisms that control the phosphorylation of EWSR1/FLI1-Thr 79, thereby regulating its activity and promoting mitotic dysfunction, is essential for understanding the pathogenesis of Ewing sarcoma." (PMID 33293370, 2021). "We identified EWSR1/FUS-ETS fusion transcripts in all cell lines and pathologically defined Ewing sarcoma tumors that were tested." (PMID 34749732, 2021).